FGFR3 (fibroblast growth factor receptor 3)
Diseases named in the same sentence as FGFR3 in open-access papers (continued):
Sharing a sentence is not in itself a finding about the gene and the disease.
tumor (continued). "Considering that TLR3 agonists are promising in clinical treatment as immunoadjuvants, our results may provide guidance for developing novel immunotherapy strategies for MIBC patients with FGFR3 mutations and promoting individualized tumor immunotherapy in the future." (PMID 37283287, 2023). "These tumor-associated FGFR3 activation signatures suggest that C0 may respond to FGFR inhibitors." (PMID 36245985, 2022). "Despite the slight impact of rogaratinib monotherapy on tumor cells with FGFR3 mutation when baseline parameters are used, our model simulations show that its combination with anti-PD-L1 therapy increases the effect size of the anti-PD-L1 therapy on tumor cells with the FGFR3 mutation." (PMID 34984415, 2021). "Moreover, the exuberant PSMA-positive neovascularization could be explained by the role of the gene FGFR3 and its mutations at the level of BCa cells, an indirect marker of tumor aggression implicated in the neo-angiogenesis process." (PMID 33963223, 2021). "Studies on genomic and transcriptional profiles of the tumour samples generated in this study may be useful in order to gain further mechanistic insights into the suppression of acute inflammation and tumourigenesis in the presence of FGFR3 mutations." (PMID 30043421, 2018). "In order to determine whether an S249C mutation in FGFR3 drives tumour pathogenesis in the bladder, we generated a transgenic mouse line that expresses the human FGFR3 IIIb isoform with an S249C mutation under control of the mouse uroplakin II promoter Tg(UroII‐hFGFR3IIIbS249C) (‘FGFR3S249C’)." (PMID 30043421, 2018). "Therefore, the effects of individual FGFR3 mutations in regulating neutrophils and tumour pathogenesis are distinct and may explain the low frequency of kinase domain mutations in human bladder neoplasia." (PMID 30043421, 2018). "Our results provide direct in vivo evidence indicating that FGFR3 mutations by themselves have very limited tumorigenic activity and they require specific collaborative events, particularly deficiencies in one or more tumor suppressive pathways, in order to initiate urothelial tumors." (PMID 27157475, 2016). "In addition, other technical biases such as tumor cell percentages and DNA quality might significantly affect accurate detection of the FGFR3 mutation, too." (PMID 27029078, 2016). "However, in CRC the FGFR3 IIIc variant was found to increase predominantly in a subgroup of advanced tumors and to exert oncogenic functions by a gain of broader ligand specificity important for tumor progression." (PMID 27650542, 2016). "Therefore we correlated FGFR3 mutation status with tumour grade." (PMID 24650297, 2014). "However, unique outcomes are also possible given the different cell contexts, the tumor type, and the fact that FGFR3 mutations are associated with an early stage and less aggressive form of cancer in the bladder, while in MM, FGFR3 mutations are more associated with cancer progression." (PMID 24466111, 2014). "However, while superficial tumours tend to exhibit activating mutations of FGFR3, often accompanied by protein upregulation, invasive tumours more commonly show upregulation of wild-type FGFR3." (PMID 22899908, 2012). "Furthermore, FGFR3 mutations are extremely common in the most benign bladder lesions (low malignant potential neoplasms and urothelial papillomas) and low-grade and -stage tumours (PUNLMP; TaG1), reaching frequencies over 80% in these subgroups." (PMID 22899908, 2012).
tumor (continued). "In hepatocellular carcinoma, FGF9 activation of both FGFR3-IIIb and IIIc isoforms stimulates tumor growth and neovascularization." (PMID 41584352, 2026). "They highlight the therapeutic potential of targeting FGFR3 isoform-specific signaling to simultaneously restrain tumor growth and reprogram the tumor immune microenvironment." (PMID 41584352, 2026). "In terms of cell signaling and gene regulation, aberrant activation of signaling pathways (notably FGFR3 mutations or fusions, HRAS overexpression, and alterations in MAPK components such as MAP4K3) further promotes tumor growth and progression." (PMID 41590518, 2026). "LZU‐WZLYCS01 is designed to achieve precise drug delivery through FGFR3 targeting while simultaneously leveraging A2‐mediated MAD2L1 inhibition to eradicate tumor cells, providing a promising therapeutic strategy to address these molecularly driven challenges." (PMID 41168906, 2026). "At the same time, upregulation of the FGFR3-IIIc isoform broadens ligand-binding specificity and triggers multiple oncogenic pathways, further enhancing tumor aggressiveness." (PMID 41584352, 2026). "In luminal muscle‐invasive bladder cancer (MIBC), lncRNA profiling identified a subset of tumours with more favourable outcomes and enriched FGFR3 signalling, suggesting potential candidates for FGFR3‐targeted therapy." (PMID 41425537, 2025). "Tumor- and CRC-specific mutations were mostly synonymous or low-impact variants in genes including AKT1 (YCLO-2), BRAF (YCLO-2), FGFR3 (YCLO-7), and PIK3R1 (YCLO-7)." (PMID 40462147, 2025). "Co-culture of B cells and melanoma cells leads to reciprocal changes in both cells, whereby tumor cell secretion of FGF2 induces B cell increases in FGFR1/FGFR3 signaling and IGF1, IL-1α/β and PDGF-A/B expression." (PMID 40663561, 2025). "A preclinical study showed that FGFR inhibitors increased anti-PD-1 treatment efficacy in an FGFR3 mutant-driven murine high-grade NMIBC model by abrogating ICI-induced regulatory T cell (Treg) expansion in the tumor microenvironment." (PMID 40603902, 2025). "The aim of this study was to evaluate the diagnostic potential of a urinary tumor DNA detection panel, which included eight common point mutations in TERT, GPR126, FGFR3, and PIK3CA genes, in UBC." (PMID 41515564, 2025). "AZD4547, a pan-FGFR inhibitor targeting FGFR3 tyrosine kinases and inhibiting tumor growth, is undergoing clinical trials in patients with multiple cancers featuring FGFR alterations." (PMID 40943615, 2025). "Out of 19 moderately stained FGFR3 tumours, 8 were high-grade, with 11 being low-grade ones and zero positivity in CIS cases." (PMID 41375830, 2025). "This highly selective targeting of FGFR2 and FGFR3 translates into superior efficacy and improved tolerability in genetically defined tumor subtypes." (PMID 41514604, 2025). "Overcoming tumor resistance to ADCs and FGFR3 inhibitors to increase clinical response rate requires a multifaceted approach." (PMID 41409251, 2025). "In contrast, Cluster 2-Sub 2 combined FGFR3 mutations, high TMB, and limited immune suppression, highlighting the importance of a less suppressive tumor microenvironment." (PMID 41567195, 2025).
tumor (continued). "This suggests that either FGFR3 or RAS activation is sufficient for tumorigenesis in each tumour, but both are rarely found together." (PMID 41008920, 2025). "In vitro and animal models have confirmed that targeted knockout of oncogenes such as FGFR3 or Gαi3 using CRISPR-Cas9 inhibits tumor growth." (PMID 41438986, 2025). "In particular, of the nine tumours with strong FGFR3 positivity, six were low-grade, two were high-grade, and one was CIS." (PMID 41375830, 2025). "Most studies suggested that elevated IRTKS expression or the activated fusion gene FGFR3-BAIAP2L1 promoted tumor growth and progression by activating FGFR3, epidermal growth factor receptor (EGFR) signaling, and known membrane protrusions." (PMID 39192031, 2024). "FGFR3 expression has been correlated with tumor growth in different cancer types and is a known regulator of the NF-κB pathway." (PMID 38542061, 2024). "FGFR3 overexpression initiates a series of cascades, including abnormal neuronal precursor cell proliferation, angiogenesis, tumor cell migration, differentiation, survival, and activates pathways such as the PI3K-AKT1 pathway." (PMID 38609519, 2024). "R3Mab (MFGR1877S) is a recombinant human antibody designed to selectively bind to the IgII and IgIII domains of FGFR3 shown to exhibit anti-tumor activity in in vitro studies, in BC models and in mouse xenograft models." (PMID 39764422, 2024). "scRNA-seq of erdafitinib-treated UPFL tumors confirms that oncogenic FGFR3 drives luminal gene expression across the spectrum of basal to luminal tumor cells." (PMID 38226620, 2024). "In order to more directly assess the role oncogenic FGFR3 was playing in subtype-specific cells, we treated tumor-bearing UPFL mice with vehicle or erdafitinib, a small-molecule inhibitor of FGFR (n = 2 per group)." (PMID 38226620, 2024). "Despite having a relatively non–T cell–inflamed tumor microenvironment profile, studies have confirmed that FGFR3-altered tumors respond as well as FGFR3-WT tumors to ICI." (PMID 38226620, 2024). "Preclinical studies have demonstrated its anti-tumor activity in xenograft models of BC and its anti-proliferative effect on FGFR3 cancer cell lines." (PMID 39764422, 2024). "Expression of radial glial cell signature genes (PAX6, SOX2, FABP7) and FGFR3 was confirmed in both the radial glial/astrocyte-like and tumor cell clusters, whereas PIK3R3 and AKT1 were only expressed in the tumor cell cluster." (PMID 38609519, 2024). "While FGFR3-targeting therapeutics exist, their utility in this case is unclear since the fusion only exists in the epithelial subset of the tumor." (PMID 38845695, 2024). "The model predicts that highly antigenic tumors that elicit a perforin-based response from CTLs respond to ICI unless constitutively active FGFR3 signaling greatly accelerates tumor cells cycling." (PMID 38515743, 2024). "In contrast, in pediatric setting and in young adults, the finding of a FGFR3::TACC3 fusion in a tumor displaying pathological features of LGG (whatever the neuroradiological findings) leads to major difficulties in its classification." (PMID 36647073, 2023). "The molecular mechanism, at least in part, involves the alleviation of constitutive RAS/MAPK signal activity in tumor cells via FGFR3 gene silencing." (PMID 36675289, 2023).
tumor (continued). "According to another NMIBC classification called the UROMOL algorithm, class 1 includes mainly low-grade Ta tumours with significantly higher FGFR3 gene expression than other groups." (PMID 36928373, 2023). "Further, IHC assay was used to evaluate the protein levels of Fgfr3 and Fgfr4 in tumour sections derived from WT and Kdm6a CKO mouse HCC tissues." (PMID 37846441, 2023). "Here, we quantitatively analysed the tumour-immune phenotypes of sq-BLCA and correlated them with PD-L1 expression and FGFR3 mutation status." (PMID 36726072, 2023). "While numerous fusion partners have been described for both FGFR2/3, one of the most common fusion partners with FGFR3 across multiple tumor types is transforming acidic coiled-coil-containing protein 3 (TACC3)." (PMID 37980380, 2023). "The receptor, FGFR3, has high expression in cholangiocytes and lower expression in endothelial cells, in tumor and non-tumor tissue." (PMID 37770545, 2023). "As one example of the relatively high rate of false-positive signals, we experienced false-positive signals of IGH/FGFR3 in approximately 30% cells of tumor cells in KMS-21BM cells, while the false-positive rates were around 20% in patient-derived BM cells." (PMID 36882509, 2023). "Differently, C3 was featured as low immune and stromal scores, high mutation burden of FGFR3, luminal subtypes of BLCA, activation of fatty acid metabolism pathway, early stage of tumor, as well as a highest survival rate." (PMID 37091788, 2023). "In contrast, FGFR3 alterations were significantly correlated with lower pT stage, lower tumor grade, and expectedly longer survival in BLCA." (PMID 37637034, 2023). "Fibroblast growth factor receptor-3 (FGFR-3) is one of the four highly conserved fibroblast growth factor receptor tyrosine kinases (RTKs) and has been shown to have a role in tumor growth and survival regulations." (PMID 37370778, 2023). "FGFR3 is considered an oncogene but has also tumor-suppressive properties in cells with epithelial phenotype." (PMID 37671056, 2023). "We then established xenografts from the FGFR3 fusion-positive BC cells and further validated that the combinational treatment can significantly enhance the inhibition of tumor growth and prolong the survival in vivo." (PMID 37479885, 2023). "Of note, when FGFR3 is downregulated in OS cell lines (by long noncoding, microRNA or iRNA), there is a reduction in tumor growth and angiogenesis, reinforcing its relevance to this disease." (PMID 36839989, 2023). "The microscopic observation clearly showed that FGFR3 expression was seen in the cytoplasm of most tumor cells at all stages, and the FGFR3 antigenic intensity significantly increased along with the malignancy of UTUC." (PMID 36675289, 2023). "Simultaneously, BC patients with FGFR3 alterations are remarkably correlated with lower tumor stages and grades, are genetically stable, and have longer disease-specific survival." (PMID 35958598, 2022). "Anlotinib targeted FGFR3 in the treatment of OSCC and inhibited tumor cell proliferation and promoted apoptosis by inactivating the FGFR3/AKT/mTOR signaling pathway." (PMID 36167542, 2022). "In this study, FGFR3 expression was maintained upon UTUC tumor origin, UTUC metachronous IVR, and UTUC metachronous MIBC progression (117/214 (54.7%) UTUC tumor origin, 52/94 (55.3%) IVR, and 9/18 (50.0%) UTUC metachronous MIBC)." (PMID 35563543, 2022).
tumor (continued). "Both wild-type and mutant FGFR3 are expressed on tumor cells, suggesting that overexpression plays the main role in the tumorigenesis, not particularly the mutation." (PMID 35326568, 2022). "We analyzed FGFR3 in combination with clinicopathological features and found that FGFR3 expression increased and then decreased gradually with the advancement of the tumor stage." (PMID 35991125, 2022). "In FGFR3-mutated tumor PDXs, an anti-FGFR and anti-EGFR combination therapy improves tumor response compared to FGFR inhibition alone." (PMID 36033544, 2022). "The fusion protein leads to the constitutively activated kinase signaling of FGFR3 and thereby promotes cell proliferation and tumor progression." (PMID 35955806, 2022). "As expected, somatic mutations in TERT promoter, FGFR3, and CDKN2A identified in the normal urothelium were consistently detected in tumor specimens in many cases." (PMID 36198773, 2022). "However, FGFR3 alterations were closely associated with lower pT stage, tumor grade, and other favorable clinical features and outcomes, altogether, it was highly recommended that UC patients with FGFR3-altered tumors would be more likely to benefit from anti-FGFR3 therapy." (PMID 36818471, 2022). "Previous studies have explored biomarkers such as tumor mutation burden (TMB), PD-L1 expression level and fibroblast growth factor receptor 3 (FGFR3) alterations." (PMID 35223828, 2022). "NGS profiling of tumor tissue DNA identified mutations in NOTCH3 (p.G2218G), ATM (c.1236‐2A>T; intronic), and GNAS (p.R201C), in addition to amplification of FGFR3." (PMID 34765202, 2021). "In this paper, we develop a mathematical model for FGFR3-mediated tumor growth and use it to investigate the impact of the combined administration of a small molecule inhibitor of FGFR3 and a monoclonal antibody against the PD-1/PD-L1 immune checkpoint." (PMID 34984415, 2021). "The secretion of tumor growth factor (TGF‐α), Epidermal growth factors(EGF) by tumor cells, and upregulation of epidermal growth factor receptors‐like (EGFR, FGFR‐3) are implicated in the pathogenesis of TP and MAN." (PMID 33074559, 2021). "Mutations of FGFR3, STAG2, and PRKDC were significantly associated with tumor risk stage (P < 0.05)." (PMID 33407469, 2021). "FGFR3 (fibroblast growth factor receptor 3) stimulated SCD1 activity to promote tumor growth in BCa cells." (PMID 33869048, 2021). "In conclusion, these analysis results provided a critical novel understanding of FGFR3 deregulation in tumor biology and identified potential therapeutic targets and prognostic indicators for some cancer types." (PMID 34160364, 2021). "Making use of our previously published scRNA-seq data, we further found that FGFR1 expression is present among various subpopulations whereas FGFR3 is enriched in undifferentiated tumor cells." (PMID 34046693, 2021). "The skin metastasis sample showed a very similar pattern of alterations in driver genes as compared with the treated tumor, including the PIK3CA hotspot mutation, the amplifications in CCND1, EGFR, and FGFR3, and the deletions in CDK1B, CDKN2A, and CDKN2B." (PMID 34680239, 2021). "The closely related ECM and growth factors expression programs showed the most complex activity in the F2T2↑ tumor, followed by FGFR3 tumors." (PMID 33853673, 2021). "We first systematically profiled FGFR3 expression, methylation, genetic alterations, and their clinical and therapeutic implications across 32 TCGA cancer types covering 10,967 tumor samples." (PMID 34160364, 2021).